EDNRA (endothelin receptor type A)
Diseases named in the same sentence as EDNRA in open-access papers (continued):
Sharing a sentence is not in itself a finding about the gene and the disease.
acne (2 papers, 2022 to 2024). An inflammatory process of the sebaceous glands which is characterized by comedones, nodules, papules and/or pustules on the skin. "EDNRA is highlighted as a potential causal gene at the acne risk locus at 4q31.22." (PMID 35132056, 2022). "The same genetic variant that influences acne risk is also associated with EDNRA expression in both sun-exposed and non-sun-exposed skin (PPSE = 0.98, PPNSE = 0.98), with the acne risk allele associated with a decrease in EDNRA expression." (PMID 35132056, 2022).
auriculocondylar syndrome (2 papers, 2021 to 2024). Auriculo-condylar syndrome (ACS) presents with bilateral external ear malformations ('question mark' ears), mandibular condyle hypoplasia, microstomia, micrognathia, microglossia and facial asymmetry. "Genetic variants in PLCB4 have been identified as cause of the Auriculocondylar syndrome 2 (ARCND2), a disease characterized by craniofacial malformations, PLCB4 acts as a direct signaling effector of the endothelin receptor type A (EDNRA)-Gq/11 pathway." (PMID 38715801, 2024). "PLCB4, EDN, and EDNRA are closely related to human auriculocondylar syndrome (ACS, MIM #614669, #602483, #615706), which shares similar phenotypes with OAVS like ear and mandibular deformities, suggesting a functional link with ITPR1." (PMID 33747042, 2021).
endometrial cancer (2 papers, 1995 to 2023). Primary or metastatic malignant neoplasm involving the endometrium (mucous membrane that lines the endometrial cavity). "The miRNA prediction indicated that miR-485-3p, whose activity was reduced in all endometrial cancer grades, may be involved in the regulation of EDNRA expression." (PMID 36542159, 2023). "EDN1 and EDNRA were overexpressed regardless of endometrial cancer grade, which may be due to the lack of regulatory effect of miR-130a-3p and miR-485-3p, respectively." (PMID 36542159, 2023).
ischemic stroke (2 papers, 2015 to 2018). A stroke disorder caused by obstruction of blood flow to the brain, due to thrombotic (local blood clot formation) or embolic (due to a blood clot or other material traveling from another site) event. "There are several works that concern the investigation of the effect of EDN1, EDNRA, and EDNRB genetic polymorphisms on ischemic stroke (IS) development." (PMID 29849817, 2018). "In the men's subgroup, the link with ischemic stroke was revealed for the EDNRA −231A>G locus (under the recessive model)." (PMID 29849817, 2018). "At the same time, Zhang and Sui did not reveal an association between EDN1 rs5370 and EDNRA rs5335 polymorphic sites with ischemic stroke development among women of the Chinese Han population." (PMID 29849817, 2018).
meningioma (2 papers, 2018 to 2023). A generally slow growing tumor attached to the dura mater. "Interestingly, increased mRNA and EDNRA protein expression has been systematically described and associated with tumorigenesis in meningiomas." (PMID 29662628, 2018). "Many signature genes in this subpopulation, including SULT1E1, EDNRA, and EPHA7, were highly expressed in grade II/III meningioma samples." (PMID 36994665, 2023). "Six of these genes were usually underexpressed (RUNDC3B, ANGPT2, PHLDA2, CAV2, EDNRA, and SCG2) in non-aggressive/non-recurrent tumors and overexpressed in more aggressive/recurrent meningiomas." (PMID 29662628, 2018).
multiple myeloma (2 papers, 2023 to 2025). "In patients with high-risk multiple myeloma, EDNRA expression is significantly higher compared to those with low-risk MM, with the highest expression observed in focal lesions." (PMID 41459538, 2025). "The proportion of EDNRA-expressing cells and the expression of EDNRA in bone biopsies is low in premalignant stages and highest in high-risk myeloma patients." (PMID 37760488, 2023).
pulmonary disease (2 papers, 2015 to 2017). "Our study shows that EDNRA was hypomethylated in CF patients and DNA methylation levels were associated with pulmonary disease severity in blood cells." (PMID 28289476, 2017). "Previous genetic studies showed an association between EDNRA DNA polymorphisms and pulmonary disease in four independent cohorts of CF patients." (PMID 28289476, 2017). "Moreover, the DNA methylation level at three genes (GSTM3 in NEC and HMOX1 and EDNRA in blood samples) was associated with lung disease severity." (PMID 28289476, 2017). "In the METHYLCF cohort, EDNRA was less methylated in CF than in control blood samples (Wilcoxon p = 0.017) and DNA methylation level correlated with the lung disease severity (Kruskal-Wallis p = 0.028)." (PMID 28289476, 2017). "Through the analysis of 13 lung disease-modifiers genes, we found DNA methylation changes of small magnitude in two genes (HMOX1 and EDNRA)." (PMID 28289476, 2017).
stomach adenocarcinoma (2 papers, 2022 to 2024). "In stomach adenocarcinoma, endothelin receptor type A was strongly implicated in building tumor immune microenvironment." (PMID 39723204, 2024). "However, the functional mechanism of EDNRA in stomach adenocarcinoma (STAD) remains to be elucidated." (PMID 35517422, 2022).
adrenocortical tumor (1 paper, 2021). "A defect in another gene, the Endothelin receptor type A (EDNRA) gene, which encodes a G-coupled protein, was found in adrenal tissue from two siblings from a family with familial PBMAH, but its contribution to adrenocortical tumor development remains questionable." (PMID 33776926, 2021).
Airway obstruction (1 paper, 2007). Obstruction of conducting airways of the lung. "The purpose of this study was therefore to investigate whether genetic polymorphisms of preproET-1, EDNRA and EDNRB genes were associated with the degree of airway obstruction assessed by the forced expiratory volume in one second (FEV1)." (PMID 17470272, 2007). "The purpose of this study was to investigate whether the genetic polymorphisms of preproET-1, EDNRA and EDNRB genes were associated with the degree of airway obstruction, assessed by FEV1." (PMID 17470272, 2007).
angiomyolipoma (1 paper, 2018). A neoplasm with perivascular epithelioid cell differentiation often associated with tuberous sclerosis. "We have analyzed the expression of EDN1 and of its receptors EDNRA and EDNRB in primary LAM cells as well as in a TSC2 mutated cell line derived from an angiomyolipoma." (PMID 30279475, 2018).
aortic stenosis (1 paper, 2021). Aortic valve stenosis is a aortic valve disease caused by the incomplete opening of the aortic valve. "Since there is evidence that aortic stenosis is characterized by distinct upregulation of ET-1 and its target receptor Endothelin Receptor type A (ETA), promoting inflammation and fibrosis, we further searched if HG affects the endothelin system in VEC from our 3D model." (PMID 34458339, 2021).
Azoospermia (1 paper, 2021). Absence of any measurable level of sperm,whereby spermatozoa cannot be observed even after centrifugation of the semen pellet. "Furthermore, also EDNRA and TGF‐β1 gene polymorphisms seem to affect the incidence of CBAVD as well as development of the kidneys, seminal vesicles, epididymides, and ejaculatory ducts in men with azoospermia carrying CFTR mutations." (PMID 33095972, 2021).
bladder tumor (1 paper, 2022). "We compared the mRNA expression of CDH11, COL6A3, EDNRA, and SERPINF1 between bladder tumor and neighboring healthy tissues, respectively." (PMID 36595851, 2022).
breast angiosarcoma (1 paper, 2022). A malignant vascular neoplasm arising from the breast. "Interestingly, radiation-induced breast angiosarcomas have their own transcriptome signature, with a panel of deregulated marker lymphatic genes such as PROX1, podoplanin, VEGFR3, and EDNRA, which allows its discrimination from primary breast angiosarcomas." (PMID 35885529, 2022). "They observed, specifically, in radiation-induced breast angiosarcomas a concrete deregulation in the marker genes of the lymphatic endothelial cells, such as podoplanin (PDPN), PROX1, VEGFR3, and endothelin receptor A (EDNRA), which was probably induced through chronic oxidative stress." (PMID 35885529, 2022).
cerebral infarction (1 paper, 2021). An ischemic condition of the brain, producing a persistent focal neurological deficit in the area of distribution of the cerebral arteries. "Altogether, it is found that the T allele at EDNRA rs1878406 is a risk factor for cerebral infarction." (PMID 35047010, 2021).
deep vein thrombosis (1 paper, 2024). "One example of this is by targeting EDNRA expression in deep vein thrombosis (DVT) using miR-342-3p." (PMID 38540124, 2024).
dry eyes (1 paper, 2022). "In PCS/ME/CFS patients, the secretomotor symptoms (dry eyes, dry mouth) correlated negatively with levels of AABs against AGTR1, EDNRA, ADRA1A, ADRB1/2, and CHRM3 (black bars)." (PMID 36238301, 2022). "Similarly, the negative correlation of the secretomotor symptoms (dry eyes, dry mouth) with levels of AAB against vasoregulatory receptors AGTR1, EDNRA, ADRA1A, ADRB1/2, and CHRM3 indicate a vascular mechanism." (PMID 36238301, 2022).
dwarfism (1 paper, 2022). "Other regions included novel candidate genes that might contribute to the phenotypic variation among the analyzed breeds, including genes for pigmentation-related traits (EDNRA, EDNRB, MITF and OCA2) and body size, with a strong candidate for dwarfism in rabbit (COL2A1)." (PMID 35062866, 2022).
gastric ulcer (1 paper, 2020). An ulcerated lesion in the mucosal surface of the stomach. "Endothelin-1 (EDN1) and Endothelin receptor type-A (ENDRA) were also found to be upregulated and EDN1 previously was shown to contribute to the pathogenesis of hemorrhagic shock resulting from gastric mucosal damage, analogous to gastric ulcer." (PMID 33276578, 2020).
Headache (1 paper, 2014). Cephalgia, or pain sensed in various parts of the head, not confined to the area of distribution of any nerve. "As a result, we recognized totally 7 possible causing genes (CALCA, TGFBR2, TNF, ESR1, EDNRA, KCNK18, and MTHFR) of headache in the top 10 genes." (PMID 24991551, 2014).
hemochromatosis (1 paper, 2024). A disorder of iron metabolism characterized by a triad of HEMOSIDEROSIS; LIVER CIRRHOSIS; and DIABETES MELLITUS. "Seven GMs, including ABCC1, ADRB2, EDNRA, hemochromatosis (HFE), HLA, interleukin 8 (IL-8), TCF7L2, and SLC11A1, had two studies conducted." (PMID 40225935, 2024).
large artery stroke (1 paper, 2018). Stroke caused by the blockage of blood flow in one of the large arteries feeding the brain. "The aim of the present case-control study was to investigate the possible association between EDN1 rs5370 and EDNRA rs5335 polymorphisms and large artery stroke (LAS) in representatives of the Ukrainian population." (PMID 29849817, 2018). "In this study, the analysis of a possible association between EDN1 rs5370 and EDNRA rs5335 gene polymorphisms and the risk of large artery stroke (LAS) in a Ukrainian population was conducted." (PMID 29849817, 2018).
liver cancer (1 paper, 2024). An epithelial or non-epithelial malignant neoplasm that arises from the liver. "To further investigate the role of EDNRA in breast and liver cancers, we designed shEDNRA to knock down EDNRA expression in MDA‐MB‐231 and HepG2 cell lines." (PMID 39601333, 2024). "After the analysis of EDNRA level in the collected breast and liver cancer tissues, as expected, EDNRA was overexpressed in both cancer tissues, which were consistent with our previous results." (PMID 39601333, 2024).
normal tension glaucoma (1 paper, 2012). "We observed expression of seven genes which were previously genetically associated with POAG (included normal tension glaucoma (NTG)), namely APOE, CAV1, EDNRA, MYOC, OPTC and TMCO1." (PMID 23028713, 2012).
osteoarthritis (1 paper, 2021). A noninflammatory degenerative joint disease occurring chiefly in older persons, characterized by degeneration of the articular cartilage, hypertrophy of bone at the margins and changes in the synovial membrane. "Recently, evidence has emerged that the analgesic effects of TENS for knee pain associated with osteoarthritis is influenced by genetic variation within the catechol-O-methyltransferase (COMT) and endothelin receptor type A (EDNRA) genes." (PMID 33919821, 2021).
paraganglioma (1 paper, 2017). A benign or malignant neoplasm arising from paraganglia located along the sympathetic or parasympathetic nerves. "In the present study, expression of all five somatostatin receptor (SST) subtypes, chemokine receptor CXCR4 and endothelin receptor type A (ETA) was assessed by means of immunohistochemistry in a total of 66 paraffin-embedded paraganglioma samples from 55 patients." (PMID 29163802, 2017).
Tension-type headache (1 paper, 2013). A type of headache that last hours with continuous pain of mild or moderate intensity, bilateral location, a pressing/tightening (non-pulsating) quality and that is not aggravated by routine physical activity such as walking or climbing stairs. "A recent meta-analysis investigated the genetic role of the endothelin type A receptor (EDNRA) – one of the two receptors of the potent vasoconstrictor ETA-1 – in migraineurs and in patients with tension-type headache." (PMID 23848401, 2013).
Wilms tumor (1 paper, 2011). An embryonal neoplasm characterized by the presence of epithelial, mesenchymal, and blastema components. "EDNRA is directly activated by downstream targets of the WNT/beta-catenin pathway in Wilms tumors, and WNT/beta-catenin pathway could regulates the function of MyoD and myogenin in myogenesis." (PMID 21637832, 2011).
tumor (86 papers, 2003 to 2026). "Our data showed that EDNRA was inversely associated with Tumour Mutational Burden (TMB) in pan‐cancer analysis (r = −0.2, p < 0.001)." (PMID 39601333, 2024). "The results have founded that EDNRA was differentially expressed in various tumours, and highly associated with patient's age and tumour stage." (PMID 39601333, 2024). "Meanwhile, In the survival curve, the tumor-associated macrophages with high expression of EDNRA significantly affect the STAD patient's prognosis." (PMID 35517422, 2022). "Second, EDN1 and EDN2 binding to EDNRA can activate p125 focal adhesion kinase and paxillin, both of which have been associated with increased tumour cell invasion." (PMID 19527488, 2009). "Additionally, the EDNRA/ET‐1 axis participates in angiogenesis and the reprogramming of immune cells that are linked to tumours, regulating the immune microenvironment of tumours." (PMID 39601333, 2024). "This systematic approach led to a significant finding: the previously uncharacterised role of endothelin receptor A (EDNRA) signalling in mediating gastric mucosa–tumour communication." (PMID 40245183, 2025). "Conversely, downregulating EDNRA expression can significantly inhibit tumor cell growth, migration, and apoptosis, suggesting its potential as an anti-tumor target." (PMID 41515956, 2025). "Significantly, the endothelin axis demonstrates specific activation in GM‐to‐tumour communication, with EDNRA identified as a key receptor." (PMID 40245183, 2025). "Analysis showed endothelial cells and epithelial cells from GM tissue predominantly express endothelin ligands, while tumour cells highly express EDNRA, suggesting a specific paracrine signalling mechanism." (PMID 40245183, 2025). "To validate the bioinformatics results for EDNRA, we utilized six tumour cell lines and assessed the gene expression of EDNRA through qPCR." (PMID 39601333, 2024). "A study has demonstrated that EDNRA plays a critical role in tumour immune suppression by modulating the secretion of EV PD‐L1, thus impacting T cell activity and reducing the efficacy of immune checkpoint blockade therapy." (PMID 39601333, 2024). "Macitentan, a drug targeting EDNRA, has been reported in multiple studies, which can improve tumor immunotherapy outcomes and inhibit tumor metastasis." (PMID 38168907, 2024). "This study aimed to reveal the potential link between cancer immunotherapy and EDNRA in human tumours." (PMID 39601333, 2024). "An integrated study of EDNRA expression differences in normal and tumour tissues demonstrated the potential of EDNRA as an immunotherapeutic agent for a variety of tumour types." (PMID 39601333, 2024). "EDNRA plays a critical role in colorectal cancer (CRC), where its upregulation is associated with tumour progression and poor patient prognosis." (PMID 39601333, 2024). "As previously reported, the ET‐1/EDNRA axis can promote cell growth, differentiation, and invasiveness in various tumours." (PMID 39601333, 2024). "In summary, as a possible immune‐related gene, EDNRA can be used as a target for tumour immunotherapy." (PMID 39601333, 2024). "We discovered that a subset of mesenchymal cells that express the receptor EDNRA are more prevalent in bone marrow areas infiltrated with tumor cells." (PMID 37760488, 2023). "It was noted that the expression of CDH11, COL6A3, EDNRA, and SERPINF1 were negatively associated with tumor purity." (PMID 36595851, 2022). "The expression of EDNRA in STAD tissue was higher than adjacent non-tumor tissue (P<0.01), and EDNRA was mostly expressed in the cytoplasm but also stained positive in normal tissues and cancer cells." (PMID 35517422, 2022). "Multivariate Cox regression analysis identified, primary therapy outcome (HR=0.522, P = 0.018), age (HR=1.734, P = 0.017), tumor status (HR=3.642, P < 0.001), and EDNRA (HR=1.566, P = 0.049) as independent prognostic factors in OS (P < 0.05)." (PMID 35517422, 2022).